FOXO3 (forkhead box O3)
Diseases named in the same sentence as FOXO3 in open-access papers (continued):
Sharing a sentence is not in itself a finding about the gene and the disease.
breast carcinoma (continued). "Consistently, we find that FOXO3 expression is attenuated in the drug-resistant MCF-7-EpiR and MCF-7-TaxR compared to the parental MCF-7 breast cancer cells." (PMID 31312024, 2019). "As a direct target of MIR2052HG, LMTK3 regulated downstream PKC/AKT/FOXO3 and PKC/MAPK/RSK1/ERα signaling, therefore regulating ERα-positive breast cancer growth and AI response." (PMID 30944027, 2019). "To investigate this finding further, we studied the relationships between FOXO3, SIRT1 and SIRT6 expression by immunohistochemistry in a cohort of patients of different breast cancer subtypes." (PMID 31357743, 2019). "In agreement, there is also a positive correlation between FOXO3 and PERK expression at the protein and RNA levels in breast cancer patient samples." (PMID 31312024, 2019). "Our results showed that PIP5Kα is necessary for breast cancer cell proliferation, as evidenced by the increases in the cell proliferation markers E2F1, CDK1 and CCND1 and the decrease in the tumour suppressor FOXO3." (PMID 29851245, 2018). "A study has also shown that the transcription factor FOXO3 (forkhead box O3) can be regulated in concert by its pseudogene FOXO3P (forkhead box O3 pseudogene) and circRNA circ-FOXO3 to inhibit growth and angiogenesis in breast cancer." (PMID 29702599, 2018). "Because CDK2 is involved in a variety of cancers, such as breast cancer, NSCLC, and CRC, it is conceivable that circ-Foxo3 takes a part in cancers above by formation of circ-Foxo3-p21-CDK2 ternary complex." (PMID 28049499, 2017). "In agreement, our result also show that BRCA1 suppresses proliferation of basal type breast cancer cell line HCC70, at least partially through FOXO3, as depletion of FOXO3 by siRNA compromised the cell proliferation suppression induced by BRCA1 overexpression." (PMID 27043660, 2016). "Although in breast cancer, a repressive effect of FOXO3 on VEGF was reported, we observed that NB15/FOXO3 cells per se expressed higher levels of fully processed VEGF-C and hypoxia further induced the unprocessed VEGF-C variant at 58/61 kDa." (PMID 27769056, 2016). "FOXO3a (also known as FOXO3) has been described by several studies as a cell target for antitumor agents in various types of cancers, including breast cancer and chronic myeloid leukemia." (PMID 24765206, 2014). "In the present study, we focused on the influence of CHIP-induced AKT phosphorylation on FoxO3 and its downstream molecules because excessive CHIP expression and abnormal AKT activation often occur in multiple human tumors, especially in breast cancers." (PMID 24376685, 2013). "MiR-155 promoted the proliferation of breast cancer cells through down-regulation of SOCS1 (Suppressor of cytokine signaling 1) and FOXO3a (Forkhead box O3)." (PMID 21541331, 2011). "Further exploration using databases to identify downstream target genes of miR-21-3p, along with validation in cell models, identified Forkhead box class O3 (FOXO3) as a downstream target gene involved in F. nucleatum-mediated enhancement of EMT and migration in breast cancer cells." (PMID 40589632, 2025). "TCGA database analysis indicated significantly lower FOXO3 expression levels in breast cancer tissues compared to adjacent non-cancerous tissues." (PMID 40589632, 2025). "We also examined the protein levels of FoxO3 and phospho-FoxO3 in breast cancer cells lacking RHBDF1." (PMID 39420837, 2024). "Accordingly, pharmacological activation of FOXO3 has been shown to restore normal physiological conditions and reprogram ovarian and breast cancer cells into non-cancerous cells." (PMID 38466341, 2024).
breast carcinoma (continued). "Despite various studies highlighting the role of FOXO3 in breast cancer, its tumour suppressor or oncogenic mechanism is not well understood." (PMID 36727057, 2022). "The mRNA level of FOXO3 expression was observed in breast cancer and surrounding normal tissue samples." (PMID 36727057, 2022). "Notably, the downregulation of FOXO3 mRNA was more evident in the aggressive III and IV stages (61/84; 72.6%) of breast cancer." (PMID 36727057, 2022). "In addition, the downregulation of FoxO3 leads to changes in the levels of CD44/CD24, which are breast cancer stem cell markers." (PMID 36142156, 2022). "In breast cancer cells, cardamonin induces apoptosis via activation of the JNK/FoxO3 pathway." (PMID 34276667, 2021). "In agreement, the interaction between FOXO3 and PML has also been observed in breast cancer." (PMID 32372224, 2020). "Given that FOXO3 is a transcriptional repressor of CCND121, we next checked whether FOXO3 is involved in LINC01355-dependent reduction of CCND1 in breast cancer cells." (PMID 31243265, 2019). "We propose a model in which PMLIV represses breast cancer proliferation, but it may also promote long‐term survival and/or stress resistance by regulating FOXM1 and FOXO3 transcriptional programs." (PMID 30927552, 2019). "Furthermore, a significant correlation between cytoplasmic FOXO3, PERK and P-eIF2α is also observed in a cohort of HER2+ breast cancer patient tissue samples." (PMID 31312024, 2019). "In this study, we used the HER2 over-expressing breast cancer cell line, BT474 and a lapatinib resistant derivative (BT474 LapR), in an effort to investigate the functional outcome of FOXO3 acetylation as well as the role of FOXO3 acetylation in modulating lapatinib response." (PMID 31357743, 2019). "Furthermore, accumulating recent evidence suggests that a host of oncogenic and cancer-driver pathways including c-Myc, Forkhead box O3A (FoxO3a) and PI3/Akt/mTOR regulate breast cancer cell metastatic behaviour through interaction with IKKβ." (PMID 29662632, 2018). "The human breast cancer cell line MDA-MB-231 are stably transfected with circ-Foxo3, the ectopic expression of the Foxo3 circular RNA could suppress tumor growth, cancer cell proliferation and survival." (PMID 30598076, 2018). "In addition, breast cancer cells overexpressing the mutant form of FOXK2 had substantial lower protein and mRNA expression levels of FOXO3 when compared with wild-type FOXK2." (PMID 29540677, 2018). "FOXO3 has been shown to be a direct target of EGCG in tumours, like pancreatic and breast cancer." (PMID 30563268, 2018). "In agreement, our ChIP assays showed that DNMT1/3a/3b and the transcriptional repressive histone mark H3K27me3 are recruited to the promoter region of FOXO3 in BRCA1-low and -mutated breast cancer cell lines but not in BRCA1-competent MCF-7 cells." (PMID 27043660, 2016). "To establish the functional significance of BRCA1–FOXO3 regulatory axis in breast cancer, we evaluated whether the anti-proliferative function of BRCA1 is mediated through FOXO3." (PMID 27043660, 2016). "miR-222-3p can also trigger malignant transformation by altering the expression levels of genes involved in cell death and survival, such as CAV2, PTEN, FOXO3, CDK6 and promote aggressive ER-negative breast tumors by increasing proliferation and migratory activity of breast cancer cells." (PMID 27833082, 2016). "Several matching profiles (Results 2, 3, 5 and 9) implicate FoxO3 in hypoxia response: data from GDS2758 and GDS2760 compare MCF-7 breast cancer cells under hypoxic and normoxic conditions as well as with siRNAs targeting hypoxia-inducible factor 1 (HIF-1α) and HIF-2α." (PMID 21172034, 2010).
breast carcinoma (continued). "While GATA3, ESR1, PIK3CA, FOXA1, FOXO3, and RB1 protein abundances were not significantly reduced in GATA3mut breast cancers, the expression of genes associated with MDM2 function and phosphorylation of genes associated with ERK signaling and aggressive phenotypes were impacted." (PMID 40439821, 2025). "Collectively this suggests the AKT-FOXO3-FOXM1 axis plays a pivotal role in response to AKTi in ER+ breast cancer with PIK3CA mutations with and without expression of PTEN, that FOXO3 expression loss can mediate resistance, and that FOXM1 downregulation is a potential biomarker of response." (PMID 40263319, 2025). "Since most studies demonstrate the anti-cancer activity of compounds by proving the induction of FOXO3 activation through the inhibition of AKT, these results seem to be interesting and unique in that they showed the activation aspect of AKT by eugenol in breast cancer cells." (PMID 39334758, 2024). "In CRC, low expression of FOXO3 is associated with cancer progression in specimens with normal tissue, while high FOXO1 expression is associated with good prognosis in prostate and breast cancers." (PMID 37275916, 2023). "Indeed, Lin and co-workers showed that luteolin suppressed PI3K/Akt phosphorylation in an in vitro model of human breast cancer (MCF-7 cells), through the induction of forkhead box O3 (FOXO3a), followed by DNA damage; all these events culminated in mitochondrial apoptotic cascade." (PMID 37240168, 2023). "Accordingly, the absence of FOXO3 induced mammary tumor formation, suggesting that the abrogation of FOXO3-mediated autophagy could lead to mammary carcinogenesis." (PMID 34207792, 2021). "Interestingly, like FOXO3, FOXK2 has been shown to be able to repress breast cancer carcinogenesis." (PMID 32372224, 2020). "However, an increasing number of studies point out the “dark side” of FOXO3 and describe its potential oncogenic properties in different cancer types, including chronic myeloid leukemia (CML), acute myeloid leukemia (AML), breast cancer, glioblastoma, and pancreatic cancer." (PMID 31591479, 2020). "However, SIRT1 demonstrated a potential positive trend with the expression levels of cytoplasmic FOXO3 in HER2+ breast cancer subtypes with negative estrogen receptor status (ER-)." (PMID 31357743, 2019). "Moreover, correlation analysis using Gene Expression Profiling Interactive Analysis (GEPIA) indicated that a strong and positive correlation between FOXO3 and PERK mRNA expression in 1085 breast cancer cases and 291 normal breast tissue samples derived from The Cancer Genome Atlas (TCGA) database." (PMID 31312024, 2019). "Lower levels of EP300 and higher levels of the nuclear deacetylases, sirtuins (e.g., SIRT1 and SIRT6) were also detected in the BT474-LapR cells, which might also contribute to the reduced FOXO3 activity in BT474-LapR cells and therefore lapatinib resistance in HER2-positive breast cancer cells." (PMID 31357743, 2019). "Additionally, in breast cancer cells with acquired epirubicin resistance, SIRT 4, 5, 6 and 7 were found to be upregulated, particularly SIRT6, which has been shown to induce epirubicin resistance by mediating the deacetylation and inhibition of FOXO3." (PMID 29180117, 2018). "In contrast with FOXO1, FOXO3, and FOXO4, FOXO6 could therefore be an oncogene in breast cancer." (PMID 29484124, 2018). "In addition, Apigenin administration increased the expression of forkhead box O3 (FOXO3)—a transcription factor with tumor-suppressing properties that is a downstream target of Akt—via the Akt/PI3K pathway, leading to apoptosis induction in human breast cancer cells." (PMID 38791608, 2024). "Previous studies reported the overexpression of FOXO3 inhibited tumor growth in vitro and also reduced tumor size in vivo in breast cancer and thus, the lack of overexpression in our data (18%; 24/127) may point out the possible reason behind tumour progression." (PMID 36727057, 2022).
breast carcinoma (continued). "Our data suggest that FOXO3 acetylation by EP300 could be a potential marker for the identification of tumors that are likely to be sensitive to these drugs and indicate a novel therapeutic strategy to overcome lapatinib resistance in HER2-positive breast cancers." (PMID 31357743, 2019). "However, alteration of FOXO3 expression does not appear to be a major mechanism of inhibition of the biological function of FOXO3 in this cancer type, as no significant variation of the expression of this gene was observed in our large series of breast cancers." (PMID 29484124, 2018). "We also verified the negative correlation of FOXO3 and FOXM1 by Breast Cancer Gene-Expression Miner v4.9 (P < 0.01)." (PMID 37976368, 2024). "Our results strongly suggest that FOXO3 protein, but not FOXO1 protein, acts as a tumor suppressor in breast cancer." (PMID 32332845, 2020). "Altogether, these observations suggest that FOXO3 protein, but not FOXO1 protein, may act as a tumor suppressor in breast cancer." (PMID 32332845, 2020). "In fact, the strong correlation between FOXO3 and PERK expression at the mRNA level basically supports the notion that FOXO3 regulates PERK expression at the transcriptional level, which is by large independent of the breast cancer subtypes." (PMID 31312024, 2019). "Interestingly, cytoplasmic FOXO3 was found to be positively correlated with the expression levels of SIRT6 (p < 0.001) but not SIRT1 in HER2+ (ER+ and ER−) breast cancer patients." (PMID 31357743, 2019).
hepatocellular carcinoma (91 papers, 2012 to 2026). A malignant tumor that arises from hepatocytes. "FOXO3 gene polymorphisms were also investigated in multiple cancers, such as leukemia, pancreatic cancer, and hepatocellular carcinoma." (PMID 38720807, 2024). "While the overexpression of METTL3, a key m6A methyltransferase, boosts sorafenib sensitivity in hepatocellular carcinoma by stabilizing FOXO3 mRNA via m6A methylation." (PMID 40533443, 2025). "ATIC inhibits autophagy and promotes proliferation, invasion, and metastasis of hepatocellular carcinoma cells through the AKT/FOXO3 signaling pathway." (PMID 38625586, 2024). "This reduction is mediated through the AMP-activated protein kinase (AMPK) pathway and Forkhead Box O3 (FOXO3) signaling, as observed in both live rats (in vivo) and hepatoma HepG2 cells cultured in laboratories (in vitro)." (PMID 39796582, 2024). "Houttuynia cordata Thunb extract enhanced the activation of FOXO3, leading to apoptosis in HepG2 hepatocellular carcinoma cells." (PMID 39334758, 2024). "The regulation of IGFBP1 and FOXO3 revealed a novel mechanism in the ursolic acid-induced inhibition of hepatocellular carcinoma cell growth." (PMID 39334758, 2024). "FOXO3 impaired PINK1 protein stability by driving BNIP3 transcriptional repression in hepatocellular carcinoma." (PMID 36823640, 2023). "Downregulation of SIRT6 leads to an increase in doxorubicin-induced death of hepatocellular carcinoma cells by inducing FOXO3 to translocate into the nucleus and bind its target genes P27 and Bim." (PMID 35915188, 2022). "Stabilization of FOXO3 mRNA by YTHDF1 is impaired in hypoxic sorafenib‐resistant hepatocellular carcinoma due to downregulation of the RNA methyltransferase METLL3." (PMID 32368828, 2020). "On the contrary, METTL3 could also sensitizes hepatocellular carcinoma cells to sorafenib by increasing mRNA stability of FOXO3 via m6A modification." (PMID 39309428, 2024). "Therefore, the overexpression of FOXO3 due to m6A modification inhibited autophagy and promoted cell death in hepatocellular carcinoma cells." (PMID 38576024, 2024). "In HCC, metformin could regulate the expression of FOXO3 by apoptosis and pyroptosis to inhibit the development of hepatocellular carcinoma." (PMID 36385965, 2022). "For instance, in hepatocellular carcinoma, METTL3 stabilizes FOXO3 in a m6A-dependent manner, inhibiting autophagy and increasing the sensitivity of HCC to sorafenib." (PMID 38576024, 2024). "In primary hepatocellular carcinoma (HCC), METTL3 adds m6A modification to the 3′-UTR of FOXO3 mRNA, a negative regulator of autophagy, increasing its mRNA stability in a YTHDF1-dependent manner." (PMID 39686999, 2024). "In hepatocellular carcinoma (HCC) cells, the depletion of METTL3 can promote autophagy by inducing autophagy-related gene transcription and leading to forkhead box protein O3 (FOXO3) degradation via a YTHDF1-dependent pathway." (PMID 36632456, 2023). "In hepatocellular carcinoma (HCC), METTL3 depletion promoted the LC3-II accumulation by reducing the stability of FOXO3 mRNA through a YTHDF1-dependent mechanism." (PMID 36517820, 2022). "For example, 6,8-diprenylorobol indicated an anticancer effect that induced apoptosis in hepatocellular carcinoma cell lines by inhibiting cytochrome P450 family 2 subfamily J member 2 (CYP2J2) and activating forkhead box O3 (FOXO3)." (PMID 35052675, 2022). "Another study has further established that FOXO3 activation increases expression of TRAIL and cell death in response to doxorubicin in hepatocellular carcinoma (HCC), suggesting that FOXO3 is required for doxorubicin-sensitivity." (PMID 29180117, 2018). "The upregulation of FOXO1 and/or FOXO3 in cells undergoing apoptosis after blockade of the PI3K pathway suggested the involvement of FOXO1/3 in the induction of PUMA and BIM, as previously reported in cell lines derived from hepatocellular carcinoma and colorectal cancers." (PMID 36849535, 2023).
hepatocellular carcinoma (continued). "In addition, a study of hepatocellular carcinoma demonstrated that CDK9 inhibition reduced SIRT1 phosphorylation and SIRT1-mediated deacetylation of FOXO3, and inhibited FOXO3 activity and BNIP3 transcription, thereby blocking the activation of PINK1-PRKN-mediated mitophagy." (PMID 36507335, 2022). "Another study shows that FOXO3 activation increases expression of TRAIL and cell death in response to doxorubicin in hepatocellular carcinoma (HCC), suggesting that FOXO3 is required for doxorubicin sensitivity." (PMID 32372224, 2020). "Moreover, METTL3 suppresses autophagy by methylating FOXO3 (in an 800 bp region of FOXO3 3′UTR containing the m6A modification site), which subsequently downregulates the expression of ULK1, ATG5, ATG7, ATG12, ATG16L1, and MAP1LC3B in human sorafenib-resistant hepatocellular carcinoma." (PMID 35159248, 2022). "In sorafenib-resistant hepatocellular carcinoma, METTL3 was significantly down-regulated and could promote m6A modification of FOXO3 3’UTR increasing its stability via recruiting YTHDF1, thereby enhancing sorafenib resistance of HCC." (PMID 35144642, 2022).